CAT (catalase)
Diseases named in the same sentence as CAT in open-access papers (continued):
Sharing a sentence is not in itself a finding about the gene and the disease.
cancer (continued). "This review provides a description of the involvement of reactive oxygen/nitrogen species (ROS/RNS) in cancer progression and a description of the diverse functions of membrane-bound catalase in cancer cells, particularly its central role in the regulation of ROS-/RNS-mediated apoptosis signaling." (PMID 38069213, 2023). "However, CAT activity was elevated (p < 0.05) in the AM 60 mg/kg dosed group versus the cancer control rats (MTC)." (PMID 37373429, 2023). "The CAT enzyme converts hydrogen peroxide into molecular oxygen and water, thus preventing the accumulation of hydrogen peroxide that fuels aging, inflammation, and cancer." (PMID 37107290, 2023). "Regulating catalase expression to target the redox state of cancer cells." (PMID 37293508, 2023). "In addition, cancer cells often alter catalase expression, and it plays a dichotomous role in neoplastic processes." (PMID 38068888, 2023). "In addition, biochanin A (500 μg/g) has shown anti‐cancer activity in oxidative stress‐mediated cancer by up‐regulating CAT, DT‐diaphorase, GST, GPx, and SOD, along with the reduction of lipid peroxidation and lactate dehydrogenase activities significantly." (PMID 37132286, 2023). "Therefore, CAT can be used as a potential target to enhance the sensitivity of platinum-chemotherapy, nanocarriers of platinum and CAT enhance the cytotoxicity of drug resistant cancer cells." (PMID 36969849, 2023). "Interestingly, CAT has been described as downregulated in several tumoral pathologies while, at the same time, being elevated in other cancer subtypes." (PMID 36776312, 2023). "There are definite experimental results proving that CAT rs769217 can affect the prognosis of patients with biliary tr an act cancer (BTC), that knockdown of CAT induced chemoresistance through elevation of ROS level and activation of Nrf2-ABCG2 pathway in BTC cell lines." (PMID 36969849, 2023). "The Pd-Pt-GOx/HA system specifically targets CD44-overexpressed cancer cells and possesses intracellular Hyase-responsive GO, catalase (CAT), and peroxidase (POD)-like activities as well as glutathione (GSH) oxidation capacity, significantly enhancing therapeutic efficacy and biosafety." (PMID 37376161, 2023). "Cancer tissues are reported to have an altered expression level of CAT." (PMID 35370706, 2022). "Moreover, in cancer, modulating the catalase expression is emerging as a novel approach to potentiate chemotherapy." (PMID 35453573, 2022). "In line with this, some studies have reported downregulation of CAT expression in some cancers." (PMID 36112236, 2022). "Interestingly, potential catalase inhibitors in cancer are being investigated whilst there is very scanty evidence on CAT regulatory pathways in relation to drug resistance." (PMID 36112236, 2022). "Interestingly, the continual production of H2S by (NH4)2S in TME increases the amount of H2S that diffuses into cancer cells and inhibits the activity of catalase (CAT), effectively promoting the CDT effect (promote the Fenton-like reaction)." (PMID 36615526, 2022). "Genistein belonging to aglycones in fermented soymilk exhibited a higher antioxidative ability to stimulate the expression of catalase (CAT) or superoxide dismutase (SOD), which might be associated with decreased occurrence of cancer." (PMID 35956350, 2022). "On the other hand, other studies have shown a decline in catalase expression in cancer cells." (PMID 35794980, 2022). "Oppositely, the CAT and GPx-1 levels are strongly elevated in cancer cells that undergo TIS." (PMID 36230727, 2022). "MTT, NR uptake, NO, GSH, catalase, cytochrome c, comet, and caspase-3 assay were used to determine the effect of neutron radiation and also neutron and curcumin combination on the cytotoxicity of cancer cells." (PMID 36380684, 2022). "By inhibiting CAT activity, the cancer cell’s death is increased via apoptosis." (PMID 35745733, 2022).
cancer (continued). "The low levels of antioxidative enzymes like catalase and glutathione peroxidase could contribute to the greater sensitivity of cancer cells to AA+MD-driven oxidative insult, too." (PMID 35368869, 2022). "MTT, NR uptake assay, NO, GSH assay, catalase, cytochrome c, comet assay, and caspase-3 were used to determine the effect of neutron radiation and also neutron and curcumin combination on the viability of cancer cells." (PMID 36380684, 2022). "Additionally, it was found that catalase activity in cancer cells is 10–100-fold lower than in normal cells, making them over-sensitive to ascorbate." (PMID 33652579, 2021). "When cholangiocyte cell lines were treated with hydrogen peroxide for a long-term, they increased cancer cell properties such as high expression levels of antioxidant enzymes (e.g., catalase (CAT), superoxide dismutase-2 (SOD2)) and high cell proliferation rates compared to the parental cells." (PMID 33854627, 2021). "In some cancers, the antioxidant enzymes SODs, GPXs, and CAT are found to be overexpressed." (PMID 33546421, 2021). "Moreover, cancer cells generally lack catalase activity, making them extra vulnerable to oxidative stress." (PMID 34717701, 2021). "In accordance with experimental observations, cancer cells are supposed to be associated with a higher H2O2 membrane diffusion rate constant and a lower intracellular catalase concentration compared to normal cells, and we use this knowledge in the evaluation of our proposed dependent variables." (PMID 34068601, 2021). "Therefore, targeting the redox state of cancer cells by regulating the expression of catalase is a novel approach to enhance chemotherapy." (PMID 34721758, 2021). "Moreover, co-treatment with BSO and the anti-CAT compound arsenic trioxide has been shown as a new cancer treatment approach." (PMID 33546421, 2021). "The regulation of CAT expression in cancer cells is a complex process, where various mechanisms appear to be involved: a recent review explored these different crucial mechanisms in the CAT regulation, mainly via Akt/PKB in the PI3K signaling pathway in cancer cells." (PMID 34205678, 2021). "The results were contrary to previous finding, which showed that 25 μM daidzein enhanced the expression of antioxidant enzyme such as SOD3 and CAT via up-regulating Nrf2 in human cancer cell MCF7, HeLa and SK-OV-3, concomitant with improved oxidative stress condition." (PMID 33558631, 2021). "Internalized by cancer cells, the GOx/CAT-NCs facilitate microenvironmental oxidation by catalyzing endogenous H2O2 to form O2, thereby accelerating intracellular glucose catabolism and enhancing cytotoxic singlet oxygen (1O2) production with infrared irradiation." (PMID 34577080, 2021). "CAT, a regulator of catalase, plays an important role in cancer tissues." (PMID 34721758, 2021). "It was shown that normal cells are more sensitive to the induction of apoptosis with H2O2 because they are not protected with membrane-associated catalase as cancer cells." (PMID 34299530, 2021). "Here, CAT could regulate the hypoxic microenvironment of cancer by the catalytic degradation of endogenous H2O2." (PMID 34577080, 2021). "Finally, in vivo study verified that compound 4 has a promising anti-cancer activity through activating antioxidant levels (CAT, SOD and GSH) and ameliorating hematological, biochemical, and histopathological findings." (PMID 35011314, 2021). "Besides this, zinc(II) complex 12 with a novel bidentate Schiff base ligand can also inhibit CAT by the conformational changes from van der Waals forces and hydrogen bonds; it also has anti-cancer activity in human colon cancer cells." (PMID 35011380, 2021). "Pre-treatment with N-acetyl-l-cysteine and antioxidant enzymes (superoxide dismutase and catalase) suppressed AG-1-induced toxicity in cancer cells, suggesting that reactive oxygen species (ROS: superoxide and hydrogen peroxide) contribute to the toxicity of AG-1." (PMID 31991904, 2020).
cancer (continued). "Catalase deficiency leads to the steady state concentration of H2O2, which may raise various pathological conditions as cardiovascular disease, cancer, ageing oxidative, hypertension, Alzheimer, diabetes mellitus,andacatalasemia." (PMID 32922495, 2020). "Thus, it is postulated that the anti-cancer effect of CAP is due to its ability to inactivate catalase, either directly or indirectly." (PMID 33096638, 2020). "It is noteworthy that the suppression effect of CAT by H2S may also weaken the therapeutic resistance of cancer cells to ROS.[[qv: 6,8]] In consequence, the apoptosis of cancer cells is promoted by FeS@BSA nanoclusters." (PMID 32274323, 2020). "This implicates a high production of superoxide radical generated during cancer can inactivate CAT and GSH-Px and may be a probable reason for the decrease activity of these enzymes in prostate carcinogenesis." (PMID 32120827, 2020). "For cancer cells, it has been shown that catalase was silenced by a prolonged exposure to ROS through epigenetic methylation in the CpG island II in the promotor region of catalase through the transcriptional activator Oct-1." (PMID 33081384, 2020). "Meanwhile, recent studies revealed that the hypoxia condition could be relieved by highly-expressed catalase (CAT) in cancer cells which can transform intracellular H2O2 into oxygen 16-18." (PMID 32685012, 2020). "Explicitly, the model describes the catalase-dependent reaction kinetics of two apoptosis-inducing signaling pathways—the hypochlorous acid pathway, and the nitric oxide/peroxynitrite pathway—occurring in the extracellular compartment of cancer cells." (PMID 33096638, 2020). "It was found that Fe-bound NMPs (Fe-NMPs) showed outstanding peroxidase (POD)-like activity that possessed potential in antibacterial applications, and Mn-bound NMPs (Mn-NMPs) displayed catalase (CAT)-like activity with a remarkable radiotherapy sensitization effect in cancer therapy." (PMID 31901818, 2020). "More interestingly, H2S gas released intracellularly presents the specific suppression effect to catalase activity of cancer cells, resulting in the promoted presence of H2O2 that facilitates the Fenton reaction of Fe2+ and consequently promotes ROS induction within the cells remarkably." (PMID 32274323, 2020). "One of the main differences between cancer cells and normal cells that enables a selective effect of plasma on cancer over normal cells is: a) the generation of O2•‒ into the ECM and b) the presence of catalase associated to the external surface of the cell membrane." (PMID 31810265, 2019). "Also, we found that the expression levels of HSPA4 and HSP90AA1 and the detox enzyme gene CAT (catalase) are positively correlated in cancer." (PMID 31814876, 2019). "This so called “secondary” 1O2 may subsequently inactivate catalase in the cell membrane of the same cell, or the catalase in the cell-membrane of adjacent cancer cells." (PMID 31810265, 2019). "Indeed, the differential sensitivity to Asc across different cancer cells was also reflected by catalase activity." (PMID 31754384, 2019). "Interestingly, 1O2 produced during the exposure of cancer cells to the plasma-treated medium has been shown to inactivate the enzymatic activity of membrane-bound catalase, restoring the activation of the apoptotic pathway." (PMID 31687089, 2019). "Since catalase expression is sensitive to redox modulation, a therapeutic strategy may be developed in the context of cancer, taking in mind the level of catalase expression." (PMID 29535798, 2018). "Because previous results suggested that alteration of catalase gene transcription is the main regulator of catalase expression in cancer cells, we first explored the hypothesis that ATO decreased the transcriptional activity of catalase gene promoter." (PMID 29467594, 2018). "Pro-oxidant chronic treatments may lead cancer cells to acquire resistance against oxidative stress by overexpressing catalase and other antioxidant enzymes." (PMID 29467594, 2018).
cancer (continued). "Consequently, the levels of ROS, SOD2, CAT, and SULTs would be a group of closely related parameters to predict the therapeutic outcomes of resveratrol-based cancer therapy." (PMID 30116486, 2018). "SOD has powerful anti-inflammatory activity; CAT is one antioxidant enzyme, which may provide resistance against many diseases, such as cancer." (PMID 29849880, 2018). "Catalase treatment of highly metastatic cancer cell lines decreases migration and invasion." (PMID 28744456, 2017). "We also observed that expression levels of rate-limiting enzymes involved in the synthesis of other anti-oxidation factors are up-regulated in eight types of cancer, suggesting other anti-oxidation factors, such as catalase and thioredoxin, are also used to protect cancers from high levels of ROS." (PMID 29116024, 2017). "Cancer cells develop an antioxidant system comprised with ROS scavenging enzymes such as superoxide dismutases (SODs), catalase (CAT), glutathione peroxidases (GPX) as well as antioxidant agents like nicotinamide adenine dinucleotide phosphate (NADPH) and glutathione (GSH)." (PMID 28407774, 2017). "Importantly, the differences in the energetic requirements and kinetics of the PRDX/TXN/TXNRD, GPX/GSH/GSR, and catalase systems become particularly important if cancer treatments are targeting ROS metabolism by inhibiting NADPH production." (PMID 28744456, 2017). "This strongly suggests that the selective toxicity to cancer cells could be attributed to CAT downregulation, and thus the cytotoxicity of combined TETA and Asc use is primarily mediated by H2O2." (PMID 28280522, 2017). "However, a comprehensive review pointed out that the expression of catalase in other cancer cell line such as human H2O2-resistant HL-60 promyelocytic leukemia cell lines is higher than normal cell line." (PMID 27845910, 2017). "Interestingly, downregulation of SOD1 failed to ameliorate the cytotoxicity of Asc/TETA to cancer cells; in contrast, overexpression of catalase effectively halted the cancer cell death induced by Asc/TETA." (PMID 28280522, 2017). "DON treatment also resulted in decreased expression of SOD2 and CAT, which normally function to remove harmful ROS, and may thereby lower the cellular threshold for tolerating ROS for these cancer cells." (PMID 28801576, 2017). "Finally, SpCAT is inhibited in HCT-15 cancer cells, most probably through the formation of an inhibitory form of the enzyme such as CAT–Fe(III)-sulfheme-sulfide." (PMID 27848965, 2016). "The results of Western blot showed that the expressions of heme oxygenase (HO)-1, glutathione peroxidase (GPx), superoxide dismutase (SOD), and catalase (CAT) in HCC tissue elevated significantly in comparison with those in adjacent cancer tissue and normal tissue (all P <0.05)." (PMID 27227932, 2016). "Most cancer tissues contain an abundance of peroxidases and catalase." (PMID 26927177, 2016). "The analysis results demonstrated that no single study greatly influenced the overall cancer risk estimations with respect to the CAT polymorphisms, which indicates that our results are statistically robust." (PMID 27449288, 2016). "In particular, the decreased CAT is connected with the high concentration of hydrogen peroxide, which participates in the activation of pathways to lead to the proliferation, migration, and invasion of cancer cells." (PMID 27034707, 2016). "However, in the presence of CAT, a great increase in the viability was noted, 14.5% (p < 0.001) and 22% (p < 0.01) for T98G and A549 cancer cells, respectively, when compared to a plasma exposure only." (PMID 25715710, 2015). "Co-exposure with NAC or catalase blocked the PL-induced ROS increase in cancer cells." (PMID 25193861, 2014). "The relative deficit of catalase activity in some cancers – which presumably renders the hydrogen peroxide generated during i.v. ascorbate therapy more effective – likewise may be selected for." (PMID 25279352, 2014).
cancer (continued). "Rashad, El-Sayed, Mohamed, & Ali reported that quinoline derivatives inhibited the growth of MCF-7 cells by similarly increasing the activity of SOD and decreasing CAT and GPx activities, accompanied by a high production of H2O2 and other free radicals which caused cancer cell death." (PMID 24517259, 2013). "Interestingly, it also has been observed that catalase levels are modified in cancer cell lines resistant to some chemotherapeutic agents or hydrogen peroxide." (PMID 22551313, 2012). "The plant extract used in this study could have increased CAT activities possibly by directly inducing increased expression of CAT, thereby inhibiting proliferation of the cancer cells." (PMID 23153283, 2012). "The modified catalase expression in cancer cells remains puzzling but it seems that prolonged exposure to reactive oxygen species (ROS) downregulates catalase expression via hypermethylation of the catalase promoter and, in addition, transcription factors seem to be involved." (PMID 22551313, 2012). "High levels of cAT were detected in blood of patients with malignant tumors." (PMID 19183436, 2009). "In addition, stage-specific analysis further indicated that catalase activity was significantly lower across all cancer stages relative to the control group, with statistical significance noted in stage 1 (p = 0.0003), stage 2, stage 3, and stage 4 (p < 0.0001)." (PMID 41596358, 2026). "However, modulating CAT expression or exogenous supplementation may enhance therapeutic outcomes by disrupting the redox balance in cancer cells." (PMID 40722961, 2025). "In this case, the reduction in SOD and CAT activities may be early epigenetic indicators against cancerization (respectively), and GPX and GR activities that support GSH production may be a response to the possibility of oxidative stress that can induce HCC (respectively)." (PMID 37960210, 2023). "However, upon the induction of plasma to cancer cells, the enzyme ‘catalase’ will be selectively inactivated by singlet oxygen and leaves the other enzymes like superoxidase dismutases (SODs) and peroxidase (POD) to keep activating both the HOCl and ONOO− pathways." (PMID 38203693, 2023). "The effect of ROS scavengers (thiourea, catalase, and superoxide dismutase) on genistein/and daidzein-induced apoptosis of cancer cells was investigated with the explicit purpose of determining whether isoflavone-induced DNA damage in cancer cell lines involves ROS." (PMID 37049690, 2023). "However, DNA-methyltransferase inhibition does not completely restore CAT expression, thus suggesting that other mechanisms beside methylation are involved in the regulation of CAT expression in CLL, in line with the multifactorial nature of CAT expression regulation in cancer." (PMID 36112236, 2022). "Thus, the overexpression of catalase or addition of bovine catalase in media was hypothesized to partially or completely rescue cancer cells from toxicity, mediated by the combination of P-AscH− and Au." (PMID 35624835, 2022). "With the specific end goal of verifying whether the catechin-induced DNA damage in cancer cell lines also involved ROS, the effect of various scavengers of ROS (for example, catalase, thiourea, and superoxide dismutase) on EGCG-induced apoptosis of cancer cells was examined." (PMID 35327466, 2022). "Thus, singlet oxygen can eliminate cancer cells by altering the activity of catalase enzyme." (PMID 35794980, 2022). "Of these, CAT represents catalase, a key antioxidant enzyme which has been implicated in resistance to antileukemic agents such as doxorubicin, and MGLL (also known as MAGL) represents monoglyceride lipase, which has been shown to be overexpressed in aggressive cancers." (PMID 34202615, 2021). "Therefore, searching for catalase inhibitors seems reasonable in order to design synergistic agents for anti-cancer drugs, which may help to sensitize drug-resistant cancer cells." (PMID 33419097, 2021).